PCDHA1 (protocadherin alpha 1)
Description:
Potential calcium-dependent cell-adhesion protein. May be involved in the establishment and maintenance of specific neuronal connections in the brain.
Synonyms: PCDH-ALPHA1
Tractability: Antibody: UniProt places it where antibodies can reach, with high confidence; its Gene Ontology location is reachable by antibodies, with high confidence; UniProt predicts a signal peptide or a membrane-spanning region; the Human Protein Atlas places it where antibodies can reach.
Gene: Protein-coding gene on chromosome 5 (140,786,136 to 141,012,347, forward strand). Ensembl gene ENSG00000204970.
Subcellular location: Cell membrane (Isoform 1); Secreted (Isoform 2)
Subcellular location (Human Protein Atlas): Plasma membrane; Endoplasmic reticulum; Golgi apparatus; Predicted to be secreted
Gene Ontology:
Molecular function: cell adhesion molecule binding; calcium ion binding
Biological process: cell adhesion; nervous system development; homophilic cell-cell adhesion
Cellular component: plasma membrane; endoplasmic reticulum; extracellular region; membrane
Genetic constraint (gnomAD): Loss-of-function variants: 42 observed, 64.01 expected, observed/expected ratio (o/e) 0.66, 90% interval 0.51 to 0.85. The upper end of that interval is the gene's LOEUF score, 0.85, which puts it in group 3 of 6, group 1 being the genes least tolerant of losing a copy. Missense variants: 1,256 observed, 1,310 expected, observed/expected ratio (o/e) 0.96, 90% interval 0.91 to 1. Synonymous variants: 610 observed, 583.3 expected, observed/expected ratio (o/e) 1.05, 90% interval 0.98 to 1.12.
Homologues: Orthologues: mouse Pcdha1 (85% identical). Paralogues in human: PCDHA2 (83% identical), PCDHA3 (82% identical), PCDHA4 (81% identical), PCDHA13 (81% identical), PCDHA5 (81% identical), PCDHA11 (81% identical), PCDHA8 (81% identical), PCDHA6 (81% identical), PCDHA7 (81% identical), PCDHA9 (80% identical), PCDHA12 (79% identical), PCDHA10 (79% identical), and 49 more.
Diseases named in the same sentence as PCDHA1 in open-access papers:
PCDHA1 is named in the same sentence as 12 diseases in open-access papers, as found by Europe PMC text mining. Sharing a sentence is not in itself a finding about the gene and the disease. The quoted sentences say what the papers report.
gastric cancer (2 papers, 2014 to 2022). A primary or metastatic malignant neoplasm involving the stomach. "We also found six genes in MSS tumors (EYS, FAT4, FSIP2, PCDHA1, RAD50, and RECQL4) and two in MSI tumors (EXO1 and FSIP2) that were clonally mutated in multiple patients and have not been previously identified as drivers of gastric cancer or other cancers." (PMID 36970058, 2022).
bladder cancer (1 paper, 2019). "Moreover, 5-year survival rates dropped to ~ 12% in bladder cancer patients with low expression of signature 1 genes (high-risk), which included KDM8 and PCDHA1 mutations." (PMID 31036064, 2019).
bladder urothelial carcinoma (1 paper, 2019). "In bladder urothelial carcinoma, high-risk patients (low signature 1 score) harboring mutant alleles of PCDHA1 had ~ 50% increased mortality at 5 years compared to low-risk patients (high signature 1 score) with wild-type PCDHA1 (P = 0.016)." (PMID 31036064, 2019). "Although results were less dramatic for PCDHA1 and signature 2, we still observed a ~ 25% elevated mortality at 5 years for these two patient groups with bladder urothelial carcinoma (P = 0.040)." (PMID 31036064, 2019).
Chronic pain (1 paper, 2025). Persistent pain, usually defined as pain that has lasted longer than 3 to 6 months. "Among the 42 new chronic pain loci that harbor protein-coding variants, five genes (HECTD3 (chr1.p34.3), CCDC17 (chr1.p34.3), DNM1 (chr9.q33.1), PCDHA1 (chr5.q31.5), and WDR90 (chr16.p13.3)) showed evidence of colocalization in more than one brain tissue." (PMID 40297705, 2025).
gastric adenocarcinoma (1 paper, 2019). "In gastric adenocarcinoma, high-risk patients (high signature 2 scores) with mutant PCDHA1 had the worst outcomes (P = 0.002)." (PMID 31036064, 2019).
glioblastoma (1 paper, 2016). The most malignant astrocytic tumor (WHO grade IV). "Also, we used tool ‘GEO profiles’ of NCBI to search the expression of two homeobox genes (HOXA5 and HOXA10) and two cadherin genes (PCDHA1 and PCDHB13) in different grades of the glioblastoma." (PMID 27160082, 2016).
Obesity (1 paper, 2018). Accumulation of substantial excess body fat. "Moreover, we observed candidate association of rs6271 in the DBH gene, rs62618693 in the QSER1 gene, and variants in PCDHA1, RAD51B, and PLEKHA5 with non-T2D-linked obesity." (PMID 30126146, 2018). "In our study, we observed several highly case-specific variants in genes previously not directly linked to T2D and/or obesity (e.g., TMC8, PCDHA1, PLEKHA5, HBQ1, VAV3, and ADAMTS13)." (PMID 30126146, 2018).
small cell lung carcinoma (1 paper, 2018). Small cell lung cancer (SCLC) is a highly aggressive malignant neoplasm, accounting for 10-15% of lung cancer cases, characterized byrapid growth, and early metastasis. "HOTAIR is relevant to small cell lung cancer invasiveness by suppressing cell adhesion–related genes such as astrotactin 1 (ASTN1) and protocadherin alpha 1 (PCDHA1)." (PMID 29618386, 2018).
uterine corpus endometrial carcinoma (1 paper, 2019). A endometrial carcinoma (disease) that involves the body of uterus. "Conversely, PCDHA1 mutation was associated with good prognosis in uterine corpus endometrial carcinoma, hence high-risk patients with wild-type PCDHA1 had the lowest survival rates while survival was prolonged by ~ 20% in low-risk patients with mutant PCDHA1 (P = 0.003)." (PMID 31036064, 2019).
PCDHA1 also shares sentences with these, for which no sentence is quoted: cancer (2 papers); Alzheimer disease (1); glioma (1).